RPS6 (ribosomal protein S6)
Description:
Component of the 40S small ribosomal subunit. Plays an important role in controlling cell growth and proliferation through the selective translation of particular classes of mRNA. Part of the small subunit (SSU) processome, first precursor of the small eukaryotic ribosomal subunit. During the assembly of the SSU processome in the nucleolus, many ribosome biogenesis factors, an RNA chaperone and ribosomal proteins associate with the nascent pre-rRNA and work in concert to generate RNA folding, modifications, rearrangements and cleavage as well as targeted degradation of pre-ribosomal RNA by the RNA exosome.
Synonyms: S6; eS6
Tractability: Small molecule: an approved drug acts on it; a structure with a bound ligand is known; a high-quality ligand is known. PROTAC: UniProt records ubiquitination sites on it; ubiquitination databases record sites on it; its protein half-life has been measured; a small molecule that binds it is known. Other modalities: a drug acting on it is in phase 2 or 3 trials.
Target class: Other cytosolic protein
Gene: Protein-coding gene on chromosome 9 (19,375,715 to 19,380,282, reverse strand). Ensembl gene ENSG00000137154.
Subcellular location: Cytoplasm; Nucleus, nucleolus
Subcellular location (Human Protein Atlas): Cytosol; Endoplasmic reticulum
Pathways (Reactome):
Metabolism of proteins: Eukaryotic Translation Termination; Formation of a pool of free 40S subunits; Formation of the ternary complex, and subsequently, the 43S complex; GTP hydrolysis and joining of the 60S ribosomal subunit; L13a-mediated translational silencing of Ceruloplasmin expression; PELO:HBS1L and ABCE1 dissociate a ribosome on a non-stop mRNA; Peptide chain elongation; Protein hydroxylation; Ribosomal scanning and start codon recognition; SRP-dependent cotranslational protein targeting to membrane; Translation initiation complex formation; ZNF598 and the Ribosome-associated Quality Trigger (RQT) complex dissociate a ribosome stalled on a no-go mRNA
Disease: Nuclear events stimulated by ALK signaling in cancer; SARS-CoV-1 modulates host translation machinery; SARS-CoV-2 modulates host translation machinery; Viral mRNA Translation
Metabolism of RNA: Major pathway of rRNA processing in the nucleolus and cytosol; Nonsense Mediated Decay (NMD) enhanced by the Exon Junction Complex (EJC); Nonsense Mediated Decay (NMD) independent of the Exon Junction Complex (EJC); rRNA modification in the nucleus and cytosol
Cellular responses to stimuli: Response of EIF2AK4 (GCN2) to amino acid deficiency
Developmental Biology: Regulation of expression of SLITs and ROBOs
Metabolism: Selenocysteine synthesis
Signal Transduction: mTORC1-mediated signalling
Gene Ontology:
Molecular function: protein binding; protein kinase binding; RNA binding; structural constituent of ribosome
Biological process: cytoplasmic translation; positive regulation of apoptotic process; positive regulation of cell population proliferation; ribosomal small subunit biogenesis; rRNA processing; TOR signaling; glucose homeostasis; translation
Cellular component: cell body; cytoplasm; cytoplasmic ribonucleoprotein granule; cytosol; cytosolic ribosome; cytosolic small ribosomal subunit; dendrite; endoplasmic reticulum; membrane; nucleolus; nucleus; ribonucleoprotein complex; small ribosomal subunit; small-subunit processome; nucleoplasm; ribosome
Genetic constraint (gnomAD): Loss-of-function variants: 1 observed, 28.66 expected, observed/expected ratio (o/e) 0.0349, 90% interval 0.011 to 0.17. The synonymous counts are far from expectation, so gnomAD's model fits this gene poorly and the ratio says little. Missense variants: 259 observed, 330.49 expected, observed/expected ratio (o/e) 0.78, 90% interval 0.71 to 0.87. Synonymous variants: 152 observed, 109.66 expected, observed/expected ratio (o/e) 1.39, 90% interval 1.21 to 1.59.
Homologues: Orthologues: chimpanzee RPS6 (100% identical), dog RPS6 (100% identical), mouse Rps6 (100% identical), pig RPS6 (100% identical), rabbit RPS6 (100% identical), rat Rps6 (100% identical), zebrafish rps6 (96% identical), macaque RPS6 (88% identical), tropical clawed frog rps6 (85% identical), Drosophila melanogaster RpS6 (75% identical), Caenorhabditis elegans rps-6 (59% identical).
Diseases named in the same sentence as RPS6 in open-access papers:
RPS6 is named in the same sentence as 174 diseases in open-access papers, as found by Europe PMC text mining. Sharing a sentence is not in itself a finding about the gene and the disease. The quoted sentences say what the papers report.
breast carcinoma (25 papers, 2013 to 2025). "The phosphorylation of RPS6 is a marker for the activation of the IGF1R/PI3K/AKT/mTORC1 pathway associated with resistance to therapy in breast cancer." (PMID 37686596, 2023). "The level of p-RPS6 in trastuzumab-resistant HER2-positive (+) breast cancer cells inversely correlated with their susceptibility to HER2-targeting drugs." (PMID 35008473, 2021). "Phosphorylation of RPS6 has been reported to attenuate DSBs in BRCA1-deficient breast cancer cells both in vitro and in vivo." (PMID 35008473, 2021). "More importantly, data support that p-RPS6 confers olaparib-resistance to BRCA1-deficient breast cancer cells [see Section 4.3.4." (PMID 35008473, 2021). "Among these proteins, the p-RPS6 level and the degree of its response to the treated drugs could predict the susceptibility of breast cancer cells to not only trastuzumab but also other drugs, including rapamycin, AZD2014, BEZ235, erlotinib, lapatinib, MK226, and OSI-906." (PMID 35008473, 2021). "The growth inhibition evidenced in the ER + MCF7 breast cancer cells and the decrease in phosphorylation of downstream rpS6 residues confirms that targeting p70S6K1 has high therapeutic potential." (PMID 39749216, 2024). "In this retrospective observational study, conducted within a cohort of early-stage breast cancer patients, we determined phosphorylated ribosomal protein S6 (pS6) at Ser240/244 by immunohistochemistry as an indicator of PI3K pathway activation." (PMID 39448637, 2024). "Decreased phosphorylation of RPS6 was previously observed in tamoxifen-resistant breast cancer cells compared with parental cells." (PMID 36775056, 2023). "Abnormal expression of RPS6 has been indicated as a critical trigger for detachment-induced keratinization related to breast cancer development." (PMID 36775056, 2023). "More importantly, constitutive phosphorylation of RPS6 has been found to confer drug resistance in breast cancer cells, GC cells, and melanoma cells." (PMID 35008473, 2021). "RPS6 has been reported to contribute to the regulation of intraductal colonization of basal-like breast cancer cells." (PMID 35008473, 2021). "miR-152-3p has been identified as a tumor suppressor; for example, miR-152-3p was observed to negatively regulate PIK3CA expression, thus inhibiting the activation of AKT and RPS6 in breast cancer cells." (PMID 34336125, 2021). "RPS6-KD in the human breast cancer cell MCF7 and the human cervical carcinoma cell HeLa increases the number of these 5′-TOP mRNAs in actively translating polysomes." (PMID 35008473, 2021). "High-throughput proteomic analysis of breast cancer cells upon activation of RON showed robust phosphorylation of ribosomal protein S6." (PMID 30456298, 2018). "Using a detailed dissection of cellular signaling pathways in vitro and in vivo, we report that RON promotes both ligand-dependent and -independent breast cancer metastasis through activation of the mTORC1/p70S6K/rpS6 signaling axis." (PMID 30456298, 2018). "Similar to our data, the proliferation of several other kinds of cells, including breast carcinoma, cervical carcinoma and even the normal embryonic kidney cell lines, is also dramatically promoted by rpS6 phosphorylation." (PMID 26490682, 2015). "Further explorations even showed the positive rpS6-dependent cells viabilities in pancreatic and breast cancers." (PMID 26490682, 2015). "The fact that we found that RPS6 expression can predict tamoxifen sensitivity and that knockdown of RPS6 desensitized breast cancer cells to tamoxifen exposure by two folds suggests a potential role for RPS6 in the estrogen response pathway, in addition to its role as a protein synthesis regulator." (PMID 36775056, 2023). "In this context, RPS6 is used as a readout of the mTORC1 activity in many diseases, including cancer, and increased phosphorylation and/or overexpression of RPS6 has been reported in breast cancer." (PMID 36009568, 2022).
breast carcinoma (continued). "Notably, RPS6-KD is also known to upregulate RPL11 in the human breast cancer cell line, MCF7, and the human cervical carcinoma cell line, HeLa." (PMID 35008473, 2021). "MiR-129-5p sensitized HER2(+) breast cancer to trastuzumab (Herceptin) by targeting RPS6." (PMID 35008473, 2021). "Evidence from knockdown experiments supports the therapeutic potential of RPS6 targeting in various cancer cells including breast cancer, cervical carcinoma, head and neck cancer, gastric cancer, glioblastoma, HCC, hematopoietic cancer, lung cancer, melanoma, ovarian cancer, and sarcoma." (PMID 35008473, 2021). "Li found that tanshinone IIA could inhibit the angiogenesis and growth of human breast cancer xenografts in nude mice and inhibit VEGF expression in breast cancer cells via mTOR/p70S6K/RPS6/4E-BP1 signaling pathway." (PMID 27863471, 2016). "Analysis of STK11−/−/NIC mammary tumors revealed hyperactivation of mammalian target of rapamycin (mTOR) through both mTORC1 and mTORC2 pathways as determined by the phosphorylation status of ribosomal protein S6 and AKT." (PMID 23451056, 2013). "For example, over half of breast cancers demonstrate upregulated markers of mTORC1 activation, such as phospho-S6K1 and phospho-ribosomal protein S6 (rpS6), while overexpression of mTORC1 substrates are also strongly associated with prostate cancer." (PMID 28415776, 2017). "To examine the role of ribosomal protein S6 in PARP inhibitor resistance, we used a PARP inhibitor olaparib to treat HCC1937 breast cancer cell line." (PMID 24831086, 2014). "The majority of breast cancers we examined expressed RON and displayed activated mTORC1/rpS6." (PMID 30456298, 2018). "MiR-152-3p might also act as a tumor suppressor in human breast cancer cells via negatively regulating PIK3CA expression to inhibit the activation of AKT and RPS6, leading to the suppression of HCC1806 cells proliferation." (PMID 29323178, 2018). "Thus, immunoblotting of multiple mTORC1 core proteins and its downstream targets (mTOR, Raptor, p70S6K, rpS6 and 4E-BP1) revealed that the mTORC1 pathway is inhibited in matrix-deprived breast cancer cells which is suggestive of inhibition of global protein translation under matrix-detached stress." (PMID 37425300, 2023). "Furthermore, as evident from S7B–S7D Table, several late-type genes showed a significant, but opposite, association with prognosis in one or more cohorts compared to the initial analysis of breast cancer, exemplified by RPL10, EIF4B, GPBP1L1 in NSCLC and RPL3, RPS6 and STEAP1 in ovarian cancer." (PMID 27926932, 2016). "These analyses showed that our observations on RON signaling is not restricted to ER+ breast cancer cells, and revealed that RON kinase signals strongly through PI3K/mTORC1/p70S6K/rpS6 in multiple types of breast cancer cells." (PMID 30456298, 2018). "Drugs that could not downregulate p-RPS6, such as trastuzumab, erlotinib, MK2206, and OSI-906, failed to inhibit the growth of trastuzumab-resistant breast cancer cells." (PMID 35008473, 2021).
melanoma (17 papers, 2012 to 2024). A malignant, usually aggressive tumor composed of atypical, neoplastic melanocytes. "In melanomas, this can activate mTOR signaling and the subsequent phosphorylation of ribosomal protein S6 (RPS6) which results in tumor cell proliferation." (PMID 36230402, 2022). "The constitutive phosphorylation of RPS6 has been found in BRAFV600E-mutant melanoma cell clones with acquired resistance to PKIs." (PMID 35008473, 2021). "The suppression of p-RPS6 has been identified as a predictive marker for improved progression-free survival (PFS) in BRAF-mutant melanoma treated with RAF or MEK inhibitors." (PMID 35008473, 2021). "RPS6-KD alone reduced the proliferation of two human melanoma cells A375-DR and A375-TR, which are resistant to the BRAFV600E-selective inhibitor dabrafenib and the MEK1/2 inhibitor trametinib." (PMID 35008473, 2021). "More interestingly, the level of t-RPS6 itself, in addition to p-RPS6 level, was also downregulated by the afatinib+crizotinib treatment in melanoma cell lines in vitro." (PMID 35008473, 2021). "The degree of suppression of RPS6 phosphorylation was a predictable indication of the sensitivity to these drugs not only in xenograft models but also in melanoma patients in a prospective evaluation." (PMID 35008473, 2021). "In melanoma cells, PD-1 increased phosphorylation of ribosomal protein S6 (RPS6) as an effector of mammalian target of rapamycin (mTOR) signaling." (PMID 30105035, 2018). "Upon treatment with BRAFi, such melanoma cells maintain high levels of phospho ribosomal protein S6 (pS6), i.e. active mTOR signaling, which is suppressed in the BRAFi sensitive cells without stromal contacts." (PMID 26918352, 2016). "Taking into account the vital role of mTOR in the regulation of translation, we expected that inhibition of mTORC1 activity and RPS6 phosphorylation observed in melanoma cells in response to longer treatments might negatively affect the rates of protein synthesis." (PMID 32531927, 2020). "Akt, mTORC1, rpS6, S6K1, Ki67, and cyclin D levels significantly increased upon melanoma cell treatment and decreased upon MC extract administration." (PMID 39684511, 2024). "Resistance-mediating processes include the phosphorylation of ribosomal protein S6 (pS6), which is downstream of MET and mTOR signaling and was observed in progressive BRAFi-resistant melanomas." (PMID 38386085, 2024). "The levels of p-RB, cyclin D1, cyclin E, CDK2, CDK4, or CDK6 by RPS6-KD were reduced in NSCLC cells, ovarian cancer cells, and drug-resistant melanoma cells." (PMID 35008473, 2021). "It remains to be studied how RPS6 regulates the G0/G1 checkpoint regulators in NSCLC, ovarian cancer cells, and melanoma cells." (PMID 35008473, 2021). "RPS6-KD induced G0/G1 cell cycle-arrest in human NSCLC cells, ovarian cancer cells, and drug-resistant melanoma cells (see Section 5.2." (PMID 35008473, 2021). "Phosphorylation of the AMPK/mTOR/p70S6K/rpS6 protein axis was also significantly lower in memory than in naïve CD4+ T cells, with reduced proliferation in the presence of melanoma cells." (PMID 26329660, 2015). "Increased oxidative stress in melanoma cells inhibited PI3K/AKT/mTOR pathway through disruption of mTORC1 formation and phosphorylation of downstream targets p70S6K, 4EBP1 and rpS6." (PMID 25749517, 2015). "Tumor cell‐intrinsic PD‐L1 promoted basal mTORC1 activity as PD‐L1KO MB49 cells showed decreased activation (phosphorylation) of mTORC1 downstream targets RPS6 and 4E‐BP1 versus control MB49 cells and reduced phosphorylated mTOR, consistent with our prior data from melanoma and ovarian cancer cells." (PMID 33626233, 2021). "The MLV Gag protein was detected on the same level in all VLPs, while histone H3, Mcm6, Rps6 and α-tubulin were detected on lower level in VLPs without recombinant melanoma antigens (MLV Gag; first lane)." (PMID 27403717, 2016).
melanoma (continued). "In two human melanoma clones, A375-DR and A375-TR, with resistance to the BRAFi, dabrafenib, and the MEKi trametinib, respectively, p-RPS6 could not be downregulated by other MAPK pathway inhibitors." (PMID 35008473, 2021). "In addition, a recombinant PD-L1 fragment crystallizable (Fc) fusion protein induces p-RPS6 in a murine melanoma cell line in an mTOR-dependent, but not PI3K-dependent manner." (PMID 35008473, 2021). "Thus, phosphorylation of rpS6 is independent of PI3K pathway activation in these melanoma cell lines." (PMID 22475322, 2012).
glioblastoma (13 papers, 2012 to 2025). The most malignant astrocytic tumor (WHO grade IV). "SOX2 maintains glioblastoma stem cell stemness, self-renewal, and therapy resistance while phosphorylated RPS6 is associated with the activation of the STAT3 signaling pathway." (PMID 40940922, 2025). "Increasing RPS6 levels enhances sphere formation and stem-like features in glioblastoma models, with RPS6 expression particularly enriched in perivascular and perinecrotic niches where glioma stem-like cells predominate." (PMID 41589302, 2025). "For example, with glioblastoma, eS6 (RPS6), eS27 (RPS27), uS8 (RPS15A) and eL34 (RPL34) are known as oncogenic, whereas uL18 (RPL5), uS17 (RPS11), uS9 (RPS16) and uS13 (RPS18) are found to have a tumor-suppressive function." (PMID 37511213, 2023). "It is involved in regulating the development of glioblastoma and colon cancer; Ribosomal Protein S6 (RPS6) is an important protein component of the 40S small subunit and was the first ribosomal protein found to be phosphorylated." (PMID 37065902, 2023). "Very interestingly, ribosomal protein S6 (RPS6) in the mTOR signaling was observed to be highly phosphorylated upon this input in human glioblastoma initiating cells." (PMID 22912867, 2012). "mTOR activity (as assessed by the abundance of p-rpS6) was significantly higher in glioblastomas compared to anaplastic astrocytomas, while there was only a trend for higher proliferation (Ki67) in these tumors." (PMID 22825389, 2012). "Furthermore, sphere-forming assays demonstrated that siRNA-mediated reduction in RPS6 expression significantly suppressed the sphere forming potential of glioblastoma cells and strongly reduced the expression of glioblastoma stem cell markers." (PMID 40940922, 2025). "RPS6 is found to be highly expressed in glioblastoma (GBM) tissues especially in the stem cell niche." (PMID 34873618, 2021). "Western blot analysis revealed that stellettin B treatment dose-dependently downregulated Akt, mTOR, and ribosomal protein S6 phosphorylation in both the U87MG and GBM8401 glioblastoma cells within 24 h." (PMID 30769863, 2019).